PKMYT1 (protein kinase, membrane associated tyrosine/threonine 1)
Diseases named in the same sentence as PKMYT1 in open-access papers (continued):
Sharing a sentence is not in itself a finding about the gene and the disease.
cancer (48 papers, 2015 to 2026). A tumor composed of atypical neoplastic, often pleomorphic cells that invade other tissues. "Its discovery highlights the diversity and uniqueness of marine natural products as sources of drug discovery and suggests potential for rational design targeting cancer-associated proteins like PKMYT1." (PMID 40290442, 2025). "Overexpression of PKMYT1 in these cancers is typically associated with poor prognosis and disease progression." (PMID 38291367, 2024). "Functional enrichment analysis revealed that PKMYT1 expression was associated with cell cycle-related, DNA replication-related, and cancer-related pathways." (PMID 36793346, 2022). "Consistent with former findings, PKMYT1 is highly expressed and frequently mutated in multiple types of human cancers including NSCLC, which results in worse clinical outcome." (PMID 34856993, 2021). "PKMYT1, a G2/M cell cycle kinase, has been implicated in tumor progression in several cancers, but its role in CLL remains unclear." (PMID 42249771, 2026). "We identified the relationship between the PKMYT1 level and cancer-associated immune cells." (PMID 36793346, 2022). "Based on the relationship between PKMYT1 and cancer-associated immune cells, we hypothesized that PKMYT1 could be connected with immunotherapy sensitivity." (PMID 36793346, 2022). "Ablation of WEE1 and PKMYT1 expression can cause mitotic collapse and apoptosis of cancer cells." (PMID 25477524, 2015). "Currently, research on PKMYT1 inhibitors is limited, with lunresertib being the only reported effective PKMYT1 inhibitor, capable of inducing synthetic lethality in cancers with CCND1 amplification." (PMID 40702552, 2025). "ASOs targeting PKMYT1AR effectively suppressed tumor growth in preclinical models.By binding to PKMYT1AR, thereby disrupting the PKMYT1AR/miR-485-5p/PKMYT1 axis that normally promotes cancer stem cell maintenance via Wnt signaling activation." (PMID 41409273, 2025). "Protein kinase membrane-associated tyrosine/threonine 1 (PKMYT1), a member of the WEE family of kinases, has recently emerged as a potential druggable target in multiple cancers including PDAC." (PMID 40606600, 2025). "Flow cytometry revealed a significant reduction in the percentage of CD45+ cancer cells in the peripheral blood of the mice received PKMYT1‐knockdown K562 cells, compared with that in the peripheral blood of the mice of wild‐type group." (PMID 40279509, 2025). "SELENOP and CD244 were highly expressed in the adjacent cancer tissues, while PKMYT1 and LAG3 were highly expressed in the cancer tissues." (PMID 40821907, 2025). "For example, PKMYT1 showed “oncogene-like” behavior in 5 cancer types, and DNASE1L3 recurrently showed “suppressor-like” behavior in 5 cancers." (PMID 38807223, 2024). "Collectively, the data indicated a marked replication stress and replication catastrophe response to combined WEE1 and PKMYT1 inhibition that likely explains the major treatment lethality in cancer cells." (PMID 37325550, 2023). "Of special interest are the redundant and divergent roles of Wee1 and the related kinase PKMYT1, in normal tissues and in various cancer types." (PMID 35251998, 2022). "Efforts have been made to develop small molecule inhibitors of PKMYT1 as a promising anti-cancer therapy approach." (PMID 33541355, 2021). "The most upregulated kinases included Protein Kinase, Membrane Associated Tyrosine/Threonine 1 (PKMYT1) (in 17 cancers), and Maternal Embryonic Leucine Zipper Kinase (MELK) (in 16 cancers)." (PMID 33801837, 2021). "The CpG probe, cg04755561 (mapped to PKMYT1), was found to be significantly negatively correlated with the gene expression from the meQTL analysis in 13 cancers." (PMID 33801837, 2021). "Targeted inhibition of PKMYT1 activity would shorten the time between checkpoint abrogation and mitotic entry and, therefore, should preferably damage cancer cells with an already defective G1 checkpoint mechanism." (PMID 33541355, 2021).
cancer (continued). "Mechanistic study shows that PKMYT1AR/ miR-485-5p /PKMYT1 axis promotes cancer stem cells (CSCs) maintenance in NSCLC via inhibiting β-TrCP1 mediated ubiquitin degradation of β-catenin proteins, which in turn causes enhanced tumorigenesis." (PMID 34856993, 2021). "Since then, multiple studies have uncovered the oncogenic role of PKMYT1 in different types of human cancers." (PMID 34856993, 2021). "Depending on the cancer subtype, the expression of WEE1 and PKMYT1 has been linked with the activation of cellular pathways crucial for the specific disease." (PMID 32958072, 2020). "Mechanistically, PKMYT1 is highly expressed in cancer cells, and G2/M check is performed to ensure genomic stability." (PMID 31837068, 2020). "The available literature highlights a common mechanism of action of WEE1/PKMYT1 inhibitors in cancer cells either in single agent or in combination with DNA damaging agents (chemotherapy/radiotherapy)." (PMID 32958072, 2020). "The identification of molecular vulnerabilities in cancer patients will be fundamental to design novel therapeutic regimens using WEE1/PKMYT1 inhibitors in a chemo/radiotherapy-free, synthetic lethality-based approach." (PMID 32958072, 2020). "Overall, the data suggest that WEE1/PKMYT1 inhibition is a suitable pharmacological target for combination strategies in cancer." (PMID 32958072, 2020). "Other understudied kinases that score favorably in the majority of cancer cohorts include PKMYT1 (Tchem), DCLK3 (Tchem), BRSK1 (Tchem), ADCK5 (Tdark), and LMTK3 (Tbio)." (PMID 33205077, 2020). "Leukemia cells were 97-fold more sensitized compared to cytarabine control, raising expectations with regard to PKMYT1 inhibition in future cancer therapy." (PMID 29168755, 2017). "In MEC1 cells, pharmacological PKMYT1 inhibition significantly reduced cancer cell viability." (PMID 42249771, 2026). "Furthermore, it has been demonstrated in pre-clinical cancer models that PKMYT1 inhibition is a promising strategy for treating CCNE1-amplificated cancers." (PMID 41376855, 2026). "Given the growing evidence of PKMYT1 as a synthetic lethality node in replication-stressed cancers, HIT101481851 may contribute to the next-generation of precision therapeutics targeting cell cycle vulnerabilities." (PMID 40606600, 2025). "However, the molecular function of PKMYT1 itself appears to be highly context-dependent, as it stabilizes β-catenin through distinct mechanisms in different cancers." (PMID 41409273, 2025). "Additionally, the percentage of CD34+ cancer stem cells was decreased in the peripheral blood of the mice of PKMYT1‐knockdown group." (PMID 40279509, 2025). "Thus, PKMYT1 is posited as a pivotal driver of tumor aggressiveness, and targeting this kinase presents a promising avenue for the development of novel cancer therapeutics." (PMID 40664640, 2025). "Synthetic lethal approaches being investigated in tumor-agnostic studies include PARP inhibitors for BRCA1/2- or ATM-mutant cancers; ATR inhibitors for ATM-mutant cancers; and PKMYT1 inhibition for solid tumors with CCNE1 amplification, FBXW7 loss, and PPP2R1A mutations (NCT04855656)." (PMID 38938274, 2024). "Interestingly, WEE1 was upregulated in only 3/17 cancer types, whereas PKMYT1 elevated in 16/17 cancer types." (PMID 38992067, 2024). "Recent studies have confirmed that PKMYT1 inhibitors may be an effective approach for the treatment of CCNE1-amplified cancers." (PMID 39591374, 2024). "Moreover, upregulation of PKMYT1 has been shown to promote resistance of cancer cells to WEE1 inhibition." (PMID 37325550, 2023). "We conclude that PKMYT1 inhibition is a promising therapeutic strategy for CCNE1-amplified cancers." (PMID 35444283, 2022). "Previous studies reported that PKMYT1 expression was up-regulated in many cancers." (PMID 36793346, 2022). "The biological function of PKMYT1 in TNBC was similar to that of other cancers." (PMID 36793346, 2022).
cancer (continued). "Yet compared to Wee1, PKMYT1 is much less studied in the context of cancer biology." (PMID 35251998, 2022). "Therefore, to decipher the specific role of PKMYT1 in different types of human cancer, indentifying its unique interacting protein complex would be critical." (PMID 34856993, 2021). "In addition, the membrane tethered form of CD133 expression, a documented biomarker for cancer stem cell, was markedly reduced upon PKMYT1 inhibition." (PMID 34856993, 2021). "Among the 148 dark kinases included in our analysis, PKMYT1 (in 17 cancers), Mitogen-Activated Protein Kinase 15 (MAPK15) in nine cancers, CaM Kinase Like Vesicle Associated (CAMKV) in 8 cancers), PNCK and STK31 (in seven cancers) were commonly upregulated." (PMID 33801837, 2021). "PKMYT1 is overexpressed in 17 of the 20 cancers analyzed in this study." (PMID 33205077, 2020). "The biological role of WEE1 and PKMYT1 in cancer cells is not fully understood." (PMID 32958072, 2020). "Indeed, several DNA damaging agent promote the indirect activation of WEE1 and PKMYT1 kinases, as showed mostly by the activation of cell cycle checkpoints (S and G2/M checkpoints) in cancer cells." (PMID 32958072, 2020). "The distribution of somatic mutations is highly heterogeneous across cancer types (WEE1: 0.2–7.6%; PKMYT1:0.1–3.6%), with a higher frequency in uterine corpus endometrial carcinoma (UCEC) and tumors of the gastrointestinal tract (stomach and colon adenocarcinoma)." (PMID 32958072, 2020). "Indeed, cancer cells seem to be strictly dependent on the functionality of WEE1/PKMYT1 kinases to survive, especially those with alterations targeting the G1 checkpoint." (PMID 32958072, 2020). "Among them, RP-6306 developed by Repare Therapeutics is the first orally bioavailable and selective PKMYT1 inhibitor that has shown robust antitumor activity in preclinical models and is currently under evaluation in phase II clinical trials for patients with advanced cancer." (PMID 40606600, 2025). "Overexpression of PKMYT1 in PDAC correlates strongly with poor prognosis, and its inhibition has been shown to induce mitotic catastrophe and apoptosis in cancer cells dependent on the G2/M checkpoint, while sparing normal cells." (PMID 40606600, 2025). "We found significant differences in the expression of SELENOP, PKMYT1, LAG3 and CD244 between the cancer tissues and adjacent cancer tissues." (PMID 40821907, 2025). "Pharmacological inhibitors of PKMYT1 have been designed and subsequently validated in CCNE1-amplified cancer models." (PMID 38570712, 2024). "Here, we report the combinatorial drugging of PKMYT1 and WEE1 kinases, which synergistically eradicates cancer cells already at low drug dose." (PMID 37325550, 2023). "Most importantly, the reciprocal rescue experiment results based on the signaling axis of PKMYT1AR/miR-485-5p/PKMYT1 using tumor sphere formation assay, strongly support the specific role in NSCLC cancer stem cells." (PMID 34856993, 2021). "Furthermore, we found that PKMYT1 physically interacted with β-catenin proteins blocking the E3-ligase SCFβ-TrCP recognition, leading to stabilization of β-catenin proteins and constitutive activation of Wnt signaling, increased self-renewal ability of cancer stem cells in NSCLC." (PMID 34856993, 2021). "To comprehensively understand these four lncRNAs (LINC01224, CASC9, LINC00346, and TRPM2-AS) and seven target mRNAs (CCNF, PKMYT1, GCH1, TK1, PSAT1, ADAM33, and DDX11), we performed genome instability, immune, cancer stemness, and drug sensitivity analysis." (PMID 34368141, 2021). "Survival analysis also showed overexpression of PKMYT1 leads to lower overall survival in ACC, BLCA, KICH, KIRC, KIRP, LGG, and LUAD cancer types." (PMID 33801837, 2021). "Among these, the genes PKMYT1, PNCK, BRSK2, ERN2, and STK31 were significant in survival in five or more cancers." (PMID 33801837, 2021).
cancer (continued). "In neuroblastic tumors, PKMYT1 is required to stabilize MYCN protein, which is a crucial proto-oncogene for this cancer types." (PMID 32958072, 2020). "We have identified a number of protein kinase genes which are upregulated commonly in cancers and are involved in the cell cycle regulation such as PLK1, TTK, BUB1, BUB1B, and PKMYT1." (PMID 28427185, 2017). "Therefore, both WEE1 and PKMYT1 may be useful targets for anti-cancer therapy." (PMID 29168755, 2017). "Our findings not only elucidate the mechanism by which Mei exerts its antitumor effects but also provide a blueprint for the development of molecular glue‐based therapeutics targeting PKMYT1, offering new avenues for the treatment of CML and potentially other cancers." (PMID 40279509, 2025). "Additionally, PKMYT1 and WEE1 inhibition synthetically eradicates cancers with high levels of RS such as glioma and HGSOC, relatively sparing normal tissues or cancers with lower levels of RS." (PMID 38279263, 2024). "This may be due to the effects of PKMYT1 on enhancing the AKT/mTOR signaling pathway in promoting carcinogenesis and the progression of cancer cells through other pathways, such as activation of Notch signaling." (PMID 38291367, 2024). "Notably, 40 DERIs were found to be specifically detected in the nuclear fraction, and many of these were from known cancer‐related genes, including AGRN, DKC1, PKMYT1, PLK1, and MARS1." (PMID 36461702, 2023). "The DGE analysis showed the genes PKMYT1, and MELK upregulated in 17 and 16 cancers, respectively." (PMID 33801837, 2021). "Our findings reveal that PKMYT1AR/miR-485-5p /PKMYT1 axis is important for cancer stem cell maintenance and NSCLC progression both in vitro and in vivo, suggesting that PKMYT1AR, miR-485-5p or PKMYT1 could be used as novel therapeutic targets in the future." (PMID 34856993, 2021). "We confirmed that PKMYT1 is highly expressed in LUAD and firstly demonstrated that artificially silencing the expression of PKMYT1 can abrogate IR-induced G2/M phase arrest and increase the sensitivity of cancer cells to radiation." (PMID 32411179, 2020). "Co‐expression analysis showed PKMYT1 has a strong positive correlation with Polo‐like kinase 1 (PLK1), implying they may cooperate in regulating cancer cell proliferation by synchronizing rapid cell cycle with high quality of genome maintenance." (PMID 31837068, 2020). "WEE1/PKMYT1 kinases are involved in different biological processes and they seem to play diverse roles in nonmalignant and in cancer cells." (PMID 32958072, 2020). "This review recapitulates and discusses the most recent findings on the biological function of WEE1/PKMYT1 during the cell cycle and in the DNA damage repair, with a focus on their dual role as tumor suppressors in nonmalignant cells and pseudo-oncogenes in cancer cells." (PMID 32958072, 2020). "In addition, the compensatory upregulation of PKMYT1 has been demonstrated to promote acquired resistance to MK-1775.35,47,48 These evidences indicate the unignorable role of PKMYT1 and suggest that combination of BTZ with PD0166285 may be more optimal than with MK-1775 in anti-cancer therapy." (PMID 38992067, 2024).
tumor (42 papers, 2008 to 2026). "In vivo experiments showed that PKMYT1 KO markedly attenuated tumor growth although the tumors harbored oncogenic KRAS mutations." (PMID 38570712, 2024). "Based on the multi-omics analysis, we found that the expression of PKMYT1 was associated with several oncogenic or tumor suppressor gene variants." (PMID 36793346, 2022). "Studies have demonstrated that PKMYT1 is overexpressed in solid tumors, and elevated PKMYT1 levels are associated with tumor progression, metastasis, and poor prognosis." (PMID 35461324, 2022). "Further research revealed that PKMYT1 expression was linked to immune cell infiltration in the tumor microenvironment." (PMID 36793346, 2022). "Elevated PKMYT1 levels have been associated with tumor progression, a more aggressive disease, the induction of metastasis at least in NSCLS patients and, generally, with poor prognosis." (PMID 32958072, 2020). "PKMYT1 (membrane-associated tyrosine- and threonine-specific CDC2-inhibitory kinase) is a negative regulator of CDK1 which has shown activity in tumours with CCNE1 amplification, FBXW7 and PPP2R1A mutations and is already being evaluated in combination with other compounds such as chemotherapy." (PMID 41188872, 2025). "In the saline-treated group, PKMYT1 deficiency had a modest inhibitory effect on tumor growth." (PMID 40393983, 2025). "In addition, based on multi-omics analysis, we found that the PKMYT1 expression was closely relevant to several oncogenic or tumor suppressor gene variants." (PMID 36793346, 2022). "In vivo experiments using an ectopic xenograft model revealed that PKMYT1 knockdown substantially inhibited tumor growth, in terms of both volume and weight, compared with that in the group engrafted with wild‐type K562 cells." (PMID 40279509, 2025). "In such genetic contexts, PKMYT1 inhibition can force mitotic entry with unresolved DNA damage, inducing mitotic catastrophe and tumor cell death." (PMID 40606600, 2025). "This pattern suggests PKMYT1 holds potential as a clinical biomarker relevant to tumor grading and molecular subtyping." (PMID 40821907, 2025). "Specifically, Mei‐based molecular glues and Mei‐derived PROTACs, such as CRBN‐type and VHL‐type PROTACs, can be designed and synthesized to enhance the degradation of PKMYT1, thereby exhibiting more potent tumor suppressive effects." (PMID 40279509, 2025). "It sequesters tumor-suppressive miR-485-5p to stabilize PKMYT1, thereby inhibiting β-catenin degradation and driving CSC maintenance." (PMID 41409273, 2025). "Immunohistochemical (IHC) analysis revealed elevated expression of PKMYT1 in PDAC tissues compared to adjacent non-tumor tissues." (PMID 40664640, 2025). "Consistent with the in vitro results, PKMYT1 knockdown significantly delayed tumor progression in vivo." (PMID 40279509, 2025). "In conclusion, HIT101481851 represents a novel PKMYT1-targeting chemotype that demonstrates conformationally stable binding and tumor-selective cytotoxicity in PDAC models." (PMID 40606600, 2025). "We concluded that the protein kinase activity of PKMYT1 participates, at least partially, in the regulation of tumor proliferation." (PMID 38570712, 2024). "The expression level of PKMYT1 progressively increased with gradually decreased degree of tumor differentiation." (PMID 38570712, 2024). "Researchers Liu and colleagues have demonstrated the oncogenic function of PKMYT1 in HCC, highlighting that the overexpression of PKMYT1 in HCC tumor samples stimulates cell growth and mobility by triggering the β-catenin/TCF signaling pathway." (PMID 39619613, 2024). "PKMYT1 ablation inhibits tumor growth and proliferation in vitro and in vivo by regulating cell cycle progression and inducing apoptosis." (PMID 38570712, 2024).